SUMF2 (sulfatase modifying factor 2)
Description:
Lacks formylglycine generating activity and is unable to convert newly synthesized inactive sulfatases to their active form. Inhibits the activation of sulfatases by SUMF1.
Synonyms: pFGE; DKFZp566I1024
Tractability: Small molecule: it has a high-quality binding pocket. Antibody: UniProt predicts a signal peptide or a membrane-spanning region. PROTAC: ubiquitination databases record sites on it; its protein half-life has been measured.
Gene: Protein-coding gene on chromosome 7 (56,064,002 to 56,080,670, forward strand). Ensembl gene ENSG00000129103.
Subcellular location: Endoplasmic reticulum lumen
Subcellular location (Human Protein Atlas): Plasma membrane; Vesicles
Pathways (Reactome):
Metabolism: Glycosphingolipid catabolism
Metabolism of proteins: The activation of arylsulfatases
Gene Ontology:
Molecular function: identical protein binding; protein binding; enzyme inhibitor activity
Biological process: glycosphingolipid catabolic process; post-translational protein modification
Cellular component: endoplasmic reticulum; endoplasmic reticulum lumen
Genetic constraint (gnomAD): Loss-of-function variants: 41 observed, 43.46 expected, observed/expected ratio (o/e) 0.94, 90% interval 0.73 to 1.22. The upper end of that interval is the gene's LOEUF score, 1.22, which puts it in group 5 of 6, group 1 being the genes least tolerant of losing a copy. Missense variants: 411 observed, 389.94 expected, observed/expected ratio (o/e) 1.05, 90% interval 0.97 to 1.14. Synonymous variants: 146 observed, 151.17 expected, observed/expected ratio (o/e) 0.97, 90% interval 0.84 to 1.11.
Homologues: Orthologues: pig SUMF2 (89% identical), rabbit SUMF2 (86% identical), dog SUMF2 (84% identical), guinea pig SUMF2 (83% identical), mouse Sumf2 (81% identical), rat Sumf2 (77% identical), tropical clawed frog sumf2 (68% identical), zebrafish sumf2 (62% identical). Paralogues in human: SUMF1 (47% identical).
Diseases named in the same sentence as SUMF2 in open-access papers:
SUMF2 is named in the same sentence as 13 diseases in open-access papers, as found by Europe PMC text mining. Sharing a sentence is not in itself a finding about the gene and the disease. The quoted sentences say what the papers report.
allergic asthma (2 papers, 2023 to 2024). A asthma with a basis in a pathological type I hypersensitivity reaction. "SUMF2 is a member of the formylglycine-generating enzyme family and may mediate airway inflammation in allergic asthma by regulating IL-13 expression." (PMID 37168863, 2023).
Bladder cancer (2 papers, 2024 to 2025). "Moreover, among patients with bladder cancer, the low SUMF2/high FBXW7 group was associated with longer OS than the high SUMF2/low FBXW7 group." (PMID 39915362, 2025). "To evaluate the potential function of SUMF2 in bladder cancer cell lines, we used a BioGRID CRISPR screen summary dataset." (PMID 39915362, 2025). "Immunohistochemical staining revealed that SCD, SUMF2, and KDEL2R were significantly more expressed in bladder cancer tissues compared to paracancerous tissues, while TM4SF1 exhibited higher expression in paracancerous tissues than in tumor tissues." (PMID 39104534, 2024). "Bladder cancer tissues from three different patients (#1, #2, and #3) exhibited markedly higher levels of SCD, SUMF2, and KDEL2R compared to the corresponding paracancerous tissues." (PMID 39104534, 2024).
breast carcinoma (2 papers, 2019 to 2023). "Our data shows that the proteins with the highest fold change in breast cancer were carbonic anhydrase 13 (CA13), sulfatase-modifying factor 2 (SUMF2), and synaptosomal-associated protein 23 (SNAP23)." (PMID 37064098, 2023).
asthma (1 paper, 2024). "Despite considerable progress in understanding the metabolic functions of pFGE (SUMF2 expression) in the past decade, its involvement in allergic inflammation in asthma remains poorly elucidated." (PMID 38540990, 2024). "Despite the advances made in researching the metabolic functions of pFGE (SUMF2 expression) over the past decade, the precise role of SUMF2 in allergic inflammation in asthma remains unclear." (PMID 38540990, 2024).
colorectal cancer (1 paper, 2022). A primary or metastatic malignant neoplasm that affects the colon or rectum. "Moreover, Chromobox Protein Homolog 5 (CBX5) is elevated in colorectal cancer and supports tumor stem-like properties in lung cancer, and SUMF2 is highly mutated in colorectal cancer." (PMID 35624824, 2022).
keloid (1 paper, 2023). An irregularly shaped, elevated mark on the skin caused by deposits of excessive amounts of collagen during wound healing. "A strong correlation between IL-7 and GLTP, GALC, ARSA, HEXB, and SUMF2 was found, suggesting that IL-7-based inflammatory factors may involve in keloid growth and development through associating with the GSL metabolism pathway." (PMID 37168863, 2023). "We explored the potential role of GSL metabolism pathway in keloid, classfied keloids based on GSLMRGs expression patterns, provided a set of gene markers including GLTP, GALC, ARSA, HEXB, SUMF2, and GBA2, and constructed a diagnostic model for keloid." (PMID 37168863, 2023). "In this study, the differential GSLMRGs of keloid and the top ten genes with the highest importance from machine learning algorithms Random Forest and SVM-RFE were intersected, and six candidate GSLMRGs were identified: ARSA, GBA2, SUMF2, GLTP, GALC, and HEXB." (PMID 37168863, 2023).
lymph node metastasis (1 paper, 2025). "The SUMF2 mRNA expression levels were associated with T status, lymph node metastasis, and worse OS in patients with BLCA." (PMID 39915362, 2025).
Multiple sulfatase deficiency (1 paper, 2021). "Combined impairment of all sulfatases, multiple sulfatase deficiency (MSD), are clinically heterogeneous disorders caused by mutations in SUMF1 or SUMF2." (PMID 33917579, 2021).
tumor (5 papers, 2010 to 2025). "In our study, we observed SUMF2 interaction with the tumor suppressor FBXW7 using a BioGRID dataset and Pathway Commons analysis." (PMID 39915362, 2025). "SUMF2 was upregulated in BLCA tumor tissues compared with normal tissues." (PMID 39915362, 2025). "Quantitative analysis of the Western blot data visually confirmed the differential expression patterns observed, with higher levels of SCD, SUMF2, and KDEL2R in tumor tissues, and higher levels of TM4SF1 in paracancerous tissues." (PMID 39104534, 2024). "Eight genes centromeric to SEPT14 (ZNF713, MRPS17, GBAS, PSPH, CCT6A, SUMF2, PHKG1 and CHCHD2) were amplified in tumour 4 only." (PMID 21170331, 2010).
cancer (3 papers, 2024 to 2025). A tumor composed of atypical neoplastic, often pleomorphic cells that invade other tissues. "Based on the SUMF2 expression levels, we used 5637 (SUMF2 high expression) cancer cells to evaluate the effect of SUMF2 on cell proliferation, migration, and invasion." (PMID 39915362, 2025). "We found that the expression of SUMF1 and SUMF2 was upregulated in 8 and 10 different cancer types, respectively." (PMID 39915362, 2025). "Although research on SUMF2 in cancer remains limited, it was found to bind to IL-13 and independently inhibit IL-13 secretion in bronchial smooth muscle cells." (PMID 39104534, 2024). "Moreover, SUMF2 knockdown significantly reduced the migration and invasion capabilities in 5637 cancer cells." (PMID 39915362, 2025). "However, SUMF2, PTP4A2, and IMP4 are associated with other types of carcinomas." (PMID 41263940, 2025). "We used the ENCORI dataset to evaluate the relationship between SUMF2 and FBXW7 in patients with BLCA and other cancer types." (PMID 39915362, 2025).
SUMF2 also shares sentences with these, for which no sentence is quoted: age-related macular degeneration (1 paper); cognitive decline (1); urothelial carcinoma (1).